PPARG (peroxisome proliferator activated receptor gamma)
Diseases named in the same sentence as PPARG in open-access papers (continued):
Sharing a sentence is not in itself a finding about the gene and the disease.
diabetes (continued). "In diabetes, the genes associated with lipid and glucose metabolism, such as PPARγ, IRS1 and IRS2 were genetic risk factors, and hepatic glutaminase mRNA was abundant during diabetes." (PMID 33466498, 2021). "The intricate protective role of PPARγ in diabetes and atherogenesis opens a promising therapeutic approach towards the treatment of CV risk associated with diabetes." (PMID 34360540, 2021). "In the pathogenesis of diabetes, downregulation of PPARγ expression is associated with excessive matrix protein accumulation and glomerulonephritis." (PMID 34680110, 2021). "Recently, an exome sequencing study has shown that the risk of diabetes was 7.22-fold higher in carriers of rare variants with reduced PPARγ function." (PMID 34764936, 2021). "It has been reported that PPARG is implicated in the pathology of obesity, diabetes, atherosclerosis and cancer." (PMID 32198386, 2020). "It has been reported that PPARγ mRNA and protein levels are downregulated by fasting and insulin-deficient diabetes." (PMID 32847136, 2020). "Based on the findings of this study, it can be concluded that the deleterious ns SNPs (rs72551364 and rs121909244SNPs) of PPARG are important candidates for the cause of different types of human diseases including diabetes mellitus." (PMID 32064572, 2020). "Polymorphisms of PPARD and PPARG are associated with risk and prognosis of many diseases, including cardiovascular disease, diabetes, brain diseases, medulloblastoma and other cancers." (PMID 32198386, 2020). "Central PPARγ stimulation induced the expression of BDNF and thus suggested a potential molecular signaling pathway, improving cognitive deficits associated with diabetes related to PPARγ." (PMID 31614739, 2019). "Subjects with GG genotype of rs2920502 in PPARγ, who had better early- and total-stage insulin secretion function and better serum lipid condition, had a decreased risk for diabetes." (PMID 29849618, 2018). "Studies with a larger sample size are needed to confirm the association of SNPs in PPARγ with diabetes." (PMID 29849618, 2018). "Most of the biochemical signatures of diabetes were reversed by pioglitazone, underlining the broad impact of PPARγ activation that is overall beneficial for metabolic parameters." (PMID 30481177, 2018). "In PPARγ, the G allele in rs2920502 decreased the risk of diabetes (OR: 0.818, 95%CI: 0.526–0.969, P = 0.042), the T allele in rs3856806 increased the risk of diabetes (OR: 1.46, 95%CI: 1.055–2.017, P = 0.022)." (PMID 29849618, 2018). "This study suggested that subjects with GG genotype of rs2920502 in PPARγ, who had better early- and total-stage insulin secretion function and better serum lipid condition, had a decreased risk for diabetes in Chinese Han population of Beijing district." (PMID 29849618, 2018). "Suppression of PPARγ activity is further intensified by JNK (c-Jun N-terminal kinase) activation via diabetes associated oxidative stress which facilitates nuclear localization and activation of FOXO1 in adipocytes." (PMID 30376839, 2018). "Current peroxisome proliferator-activated receptor (PPAR)-targeted drugs, such as the PPARγ-directed diabetes drug rosiglitazone, are associated with undesirable side effects due to robust agonist activity in non-target tissues." (PMID 30171034, 2018). "Due to the regulatory roles of peroxisome proliferator-activated receptors γ (PPARγ) in glucose and lipid metabolism, adipocyte differentiation, and inflammation, PPARγ has been shown to be associated with type 2 diabetes mellitus in a large number of studies." (PMID 29371958, 2017). "In non-MODY genes with an autosomal dominant disease inheritance, we identified one protein truncating mutation in PPARG in an individual diagnosed with diabetes at 41 years of age." (PMID 29207974, 2017). "PPARγ agonists confer benefits in diabetes and atherosclerosis, known risk factors associated with cardiovascular disease." (PMID 28243251, 2017).
diabetes (continued). "Using our approach, we identified an interaction between BMI and the Peroxisome Proliferator Activated Receptor Gamma (PPARG) gene associated with diabetes." (PMID 28953253, 2017). "Mutation of human PPARγ gene has been found to be associated with increased insulin resistance, hypertension and diabetes." (PMID 29371958, 2017). "Peroxisome proliferator-activated receptor gamma is a master regulator of adipogenesis in mammals, and mutations deleterious to PPARG function lead to increased susceptibility to diabetes and cardiovascular disease." (PMID 28588550, 2017). "Intriguingly, pioglitazone use in patients with diabetes appears to increase bladder cancer risk, further hinting that PPARG activation can promote bladder cancer growth." (PMID 29143738, 2017). "Polymorphisms of PPARγ and PPARα have also been described and found to be associated with disorders of hyperlipidemia, glucose homeostasis, and diabetes." (PMID 28781590, 2017). "PPARγ-deficient neonatal mice were rescued from embryonic lethality by epiblast-restricted recombination and showed marked lipodystrophy with diabetes but inappropriately “normal” levels of serum insulin." (PMID 27505464, 2016). "Following treatment with the anti-diabetes drug rosiglitazone – a PPARγ-agonist known to increase MAT and fracture risk – mice demonstrate a fivefold higher femur MAT volume compared to the controls." (PMID 27471493, 2016). "The third highest scoring association is PPARG-Type 2 Diabetes Mellitus (T2DM, 0.45), supported by a wealth of literature (228 articles in DisGeNET)." (PMID 25877637, 2015). "Several epidemiological studies have demonstrated that PPARG Pro12Ala is associated with insulin sensitivity and diabetes mellitus." (PMID 24447396, 2014). "This indicates a possible role of PPARγ in the development of the diabetes-associated microvascular phenotype." (PMID 24587794, 2014). "In the logistic regression models PPARG allele T was associated with odds ratio of 0.76 (95% confidence interval 0.55–1.05) for prevalent diabetes." (PMID 25197274, 2014). "One important type 2 diabetes locus is the peroxisome-proliferating-activated receptor γ(PPARγ) gene that has been associated with diabetes in GWAS studies." (PMID 23754818, 2013). "Polymorphisms in PPARG, particularly the proline-to-alanine substitution at aminoacid position 12, have been associated with diabetes, insulin levels, insulin sensitivity, body mass index, and dyslipidemia." (PMID 22523693, 2012). "It is well established that treatment of type 2 diabetes mellitus patients with TZD PPARγ agonists is associated with weight gain, in part due to increased adipogenesis/fat mass." (PMID 22489042, 2012). "One putative genetic determinant of DR in type 2 diabetes mellitus (T2DM) is the Pro12Ala polymorphism in the gene encoding peroxisome proliferator–activated receptor γ (PPARγ)." (PMID 22993484, 2012). "This review, in light of current information, focuses on the beneficial effects of PPARγ agonist in homocysteine-associated hypertension and vascular remodeling in diabetes." (PMID 20613990, 2010). "These include transcription factors concerned with the control of: adipogenesis (Pparγ, Klf15, Irf1, Creb1, Egr2, Gata3); lipogenesis (Mlxipl, Srebp1c); inflammation (Jun, Stat3); insulin signalling and diabetes susceptibility (Foxo1, Tcf7l2)." (PMID 21187013, 2010). "Based on these findings, we hypothesized that PPARγ activation contributes to protection against inflammation and fibrosis in diabetes-associated tubulointerstitial injury." (PMID 41357323, 2025). "Notably, PPARG is a regulator of adipocyte differentiation and has been implicated in the pathology of diabetes." (PMID 40628905, 2025). "In addition, SIRT6 inhibits PPARγ expression at the transcriptional level and coordinates endothelial fatty acid uptake under pathological conditions to reduce diabetes-associated HF with preserved ejection fraction (HFpEF)." (PMID 38625851, 2024).
diabetes (continued). "Regarding PPARγ mutations, women carried out 1 or several pregnancies, all complicated by diabetes, hypertension, and/or hypertriglyceridemia and frequently reported small for gestational age babies, when a fetal exposition to a dysmetabolic environment of maternal origin was present." (PMID 39479521, 2024). "As for PPARα, also PPARγ variants modulate the risk for diabetes and cardiovascular events." (PMID 36768666, 2023). "These compounds could aid in the development of PPARγ antagonists for the management ofobesity associated diabetes." (PMID 37886153, 2023). "Interestingly, the rs1801282 (Pro12Ala) PPARG variant associated with increased PPARG expression and reduced risk for diabetes and circulating triglycerides also associates with reduced albumin levels." (PMID 36413406, 2023). "Likewise, the associated target (Peroxisome proliferator-activated receptor gamma) of diabetes can be affected by 6,7-dimethoxy-2-(2-phenylethyl)chromone." (PMID 37049682, 2023). "PPARγ is a ligand-dependent nuclear transcription factor that regulates adipocyte differentiation, and its dysfunction is believed to cause numerous life-threatening diseases such as diabetes and cancer." (PMID 37649895, 2023). "We investigated whether single nucleotide polymorphisms (SNPs) and haplotypes of the PPARG gene could contribute with susceptibility to develop periodontitis alone or together with type 2 diabetes mellitus (T2DM)." (PMID 37047733, 2023). "In addition, PPARγ activation can affect the structure of osteoblasts and result in the loss of bone mass in the context of diabetes." (PMID 36951483, 2023). "The study of mice with deacetylation-mimetic PPARγ mutations K268R/K293R proved that PPARγ deacetylation can selectively regulate target genes, inhibit lipid oxidation genes with an anti-atherosclerotic effect in the treatment of diabetes, and the improvement of endothelial function." (PMID 36551260, 2022). "Many animal studies have demonstrated that PPARγ agonist might potentially reduce the risk of diabetes-induced nephropathy." (PMID 35176115, 2022). "In the Diabetes Prevention Program, the lifestyle intervention was effective in reducing type 2 diabetes incidence in individuals with higher genetic risk, such as risk variants in PPARG and TNF." (PMID 35501401, 2022). "Moreover, curcumin and resveratrol increased expression of PPARγ gene for regulation of metabolic syndrome and associated diabetes, coronary heart disease, and polycystic ovary syndrome." (PMID 36092543, 2022). "In addition, PPARG (rs1801282) was associated not only with short-term (6-month) and long-term (2-year) weight loss but also with weight regain in the Diabetes Prevention Program." (PMID 34683180, 2021). "The PPARγ agonists’ ability to inhibit inflammatory responses by repressing NF-κB target genes has been linked to the prevention and treatment of the metabolic syndrome and diabetes." (PMID 32164648, 2020). "Search for such PPARγ agonists that selectively modulate the receptor activity maintaining glucose homeostasis without the adverse effects associated with TZD is a promising approach in diabetes research." (PMID 29606113, 2018). "Subjects with TT genotype of rs3856806 in PPARγ had an increased risk for diabetes." (PMID 29849618, 2018). "The TT genotype of rs3856806 in PPARγ had an increased risk for diabetes." (PMID 29849618, 2018). "Whether UCP2 and PPARγ polymorphisms have an effect on inflammation state in diabetes remains unknown." (PMID 29849618, 2018). "The GG genotype of rs2920502 in PPARγ had a decreased risk for diabetes." (PMID 29849618, 2018). "As there is an increased risk of cardiovascular disease associated with diabetes, treatment with PPARγ agonists could complement the effects of other antiplatelet therapies in reducing the risk of thrombosis." (PMID 27896950, 2017).
diabetes (continued). "Moreover, a meta-analysis of clinical studies showed increased risk for developing heart failure in patients with diabetes treated with PPARγ agonist pioglitazone." (PMID 29093735, 2017). "Recently, in a retrospective cohort study, the prescription of the PPARγ agonist glitazone in patients with diabetes was associated with a reduction in the incidence of PD, suggesting that PPARγ pathways may be a successful drug target in PD." (PMID 27352979, 2016). "We also found that diabetes is associated with reduced expression of PPARγ." (PMID 25361524, 2014). "However, in model containing sex, age, and 2-hour insulin, PPARG allele T was significantly associated with a lower prevalent diabetes risk with an odds ratio of 0.56 (95% CI: 0.31–0.95)." (PMID 25197274, 2014). "However, a specific PPARγ variant, P121A,has also been associated with diabetes in specific populations and validated through family studies." (PMID 23754818, 2013). "Disease prediction for population subgroups based on a combined “diabetes risk matrix” including PPARG p.P12A has been proposed to be informative and might, if accompanied by lifestyle intervention, prove a worthwhile path for prevention." (PMID 22523693, 2012). "It has been demonstrated that PPARγ plays important roles in controlling lipid and glucose metabolism, and is currently known to be implicated in various metabolic diseases such as hyperlipidemia, diabetes mellitus, and coronary artery disease (CAD)." (PMID 20334678, 2010). "The PPARγ agonist rosiglitazone has been shown to decrease bone mass in mice and thiazolidinediones (TZDs) have recently been found to increase bone loss and fracture risk in humans treated for type 2 diabetes mellitus." (PMID 19331671, 2009). "Because miR-20b is linked to PPARG suppression, this pattern implies that higher miR-20b expression in untreated individuals may reduce PPARG expression, theoretically contributing to the increased diabetes risk observed in the placebo group." (PMID 41282094, 2025). "It has been demonstrated that acrolein, a volatile organic compound (VOC) clearly associated with diabetes, can induce pancreatic β-cell ferroptosis by inducing endoplasmic reticulum (ER) stress and inhibiting peroxisome proliferator-activated receptor gamma (PPARγ) expression." (PMID 39856053, 2025). "Interestingly, PPARγ mutated patients had higher adiponectin levels compared to negative patients; such data is in accordance with previous studies that described higher levels of adiponectin in relation to the PPARγ SNP in several diseases, such as diabetes." (PMID 38674417, 2024). "In a mouse model of streptozotocin-induced diabetes with hyperglycemia, high glucose not only increased neutrophil infiltration but also impaired the activity of peroxisome proliferator-activated receptor γ (PPARγ), a transcription factor for lactoferrin (Ltf) encoded by the PPARγ gene." (PMID 38965216, 2024). "In the future, the partial agonist of PPARγ (such as telmisartan, mesalazine, etc.)might be added to the treatment of clinical diabetes as a protective agent to reduce the risk of neurological complications in patients with diabetes." (PMID 35517804, 2022). "PPARγ has an immune and inflammation suppressive function, which results in an antiatherogenic effect; thus, genetic variation in the PPARγ may regulate individual susceptibility to type 2 diabetes mellitus (T2DM) and coronary heart disease." (PMID 35547362, 2022). "Thus, enhancing PPARγ pathway might be an another underlying mechanism of 9-(R)-HODE to improve diabetes." (PMID 36339561, 2022). "PPARγ activator could reduce AF susceptibility by promoting atrial cell survival and inhibit cardiac fibrosis caused by several risk factors of AF, such as diabetes, hypertension, myocardial infarction, and heart failure." (PMID 34422410, 2021).
diabetes (continued). "Six (0.6%) patients had PPARγ2 variant-induced diabetes (PPARG-DM) in the early-onset type 2 diabetes group, including three with the p.Tyr95Cys variant in activation function 1 domain (AF1), of which five patients (83%) had diabetic kidney disease (DKD)." (PMID 34764936, 2021). "In addition, applications of PPARG agonist, rosiglitazone, as anticancer treatment in clinical trials was conducted in a pilot trial and rosiglitazone was shown to reduce breast cancer risk in female patients with type 2 diabetes mellitus." (PMID 32850439, 2020). "However, these genes may play roles in diabetes; one of these genes encodes Ppm1b (protein phosphatase, Mg2+/Mn2+ dependent, 1B, Ppm1b), which increases the expression of PPARγ." (PMID 27846294, 2016). "However, PPARγ-deficient neonatal mice show severe lipodystrophy, lipemia, hepatic steatosis with focal hepatitis, relative insulin deficiency and diabetes beginning soon after birth and culminating in failure to thrive and neonatal lethality between 4 and 10 days of age." (PMID 27505464, 2016). "In addition, PPARG has been associated with other autoimmune diseases, such as inflammatory bowel disease and psoriatic arthritis, and it is also a confirmed susceptibility locus in type 2 diabetes mellitus." (PMID 24401602, 2014). "This suggests that inhibiting EGFR activation may be beneficial, not only in preventing sodium and water retention generally observed in patients with diabetic nephropathy, but also in limiting sodium and water retention associated with the use of PPARγ agonists in patients with diabetes mellitus." (PMID 23533381, 2013). "The most common population genetic variant of PPARγ is a polymorphism replacing alanine for proline at codon 12 (Pro12Ala) in PPARγ2, with a meta-analysis of association studies showing that the Pro allele confers a modest but significant increase in diabetes risk." (PMID 17011503, 2006). "PPARγ is recognized as a pivotal yet complex transcription factor, and in addition to exerting metabolic effects in diabetes, PPARγ agonists have shown potential in the treatment of neuropsychiatric disorders 28-31." (PMID 41510157, 2026). "Rosiglitazone, a PPARγ agonist, has been used clinically for the treatment of type 2 diabetes mellitus (T2DM)." (PMID 41373547, 2025). "HK2 is regulated by AKT signaling, with phosphorylated AKT promoting its mitochondrial translocation to inhibit apoptosis; its transcription is suppressed by high glucose via PPARγ, reducing its protective role in diabetes." (PMID 40940763, 2025). "Ginsenoside Rk1 has been demonstrated to enhance endothelial function in diabetes by activating PPARγ." (PMID 40405893, 2025). "Focusing on the PPARγ pathway, we identify a mechanism by which UC cells regulate NECTIN4 expression, and we evaluate the effects of PPARγ agonists, which were initially approved for diabetes, on the activity and therapeutic window of NECTIN4-CAR T cells." (PMID 40931013, 2025). "It’s worth noting that pioglitazone, a member of the thiazolidinedione class and a ligand for PPARγ, has been recognized for its beneficial effects on macrovascular complications in diabetes and has shown promise in experimental diabetic neuropathy." (PMID 39934809, 2025). "Manna reported that L‐cysteine supplementation reduced NF‐κB phosphorylation and the secretion of TNF‐α, MCP‐1, IL‐8, IL‐1β, and IP‐10 by increasing AMPK phosphorylation and PPARγ expression against vascular inflammation in diabetes mediated by PI3K." (PMID 41280738, 2025). "According to reports, betulinic acid, as a PPARγ antagonist, can inhibit diabetes by promoting osteogenic differentiation and suppressing adipogenesis." (PMID 40733369, 2025). "Background/Objectives: Rosiglitazone (RSG), a potent PPARγ agonist for type 2 diabetes mellitus (T2DM), induces adverse adipogenic effects that limit clinical use." (PMID 41471299, 2025).